LINC01505 (long independently transcribed non-coding RNA 1505)
Synonyms: uc.266; RP11-308N19.1; LOC107987108
Gene: Long non-coding RNA gene on chromosome 9 (105,993,247 to 106,771,335, forward strand). Ensembl gene ENSG00000234323.
Gene Ontology:
Biological process: SRP-dependent cotranslational protein targeting to membrane, signal sequence recognition
Cellular component: signal recognition particle, endoplasmic reticulum targeting
Diseases named in the same sentence as LINC01505 in open-access papers:
LINC01505 is named in the same sentence as 1 disease in open-access papers, as found by Europe PMC text mining. Sharing a sentence is not in itself a finding about the gene and the disease. The quoted sentences say what the papers report.
neuroblastoma (1 paper, 2018). Neuroblastoma (NB) is the most common solid, extracranial childhood tumor. "Our study finds one of those candidates, LINC01505, in a focal deletion in a neuroblastoma cell line." (PMID 30217017, 2018).